REN (renin)
Diseases named in the same sentence as REN in open-access papers (continued):
Sharing a sentence is not in itself a finding about the gene and the disease.
Hypertension (continued). "The mean age was 66.9 years old at the time of biopsy, and 64.2% were men, 29.7% had diabetes, 62.2% had high blood pressure, 12.2% were under non-steroidal anti-inflammatory drugs treatment, and 62.8% were receiving renin-angiotensin system blockers." (PMID 35629041, 2022). "The exact mechanism of vascular dysfunction in obesity is still not well clarified; however, there are some pathways such as renin–angiotensin–aldosterone system (RAAS) disorders and PVAT-derived factor dysregulation, which are involved in hypertension and endothelial dysfunction development." (PMID 34836100, 2021). "Among the 190 patients without prior hypertension, the serum levels of components in the renin-angiotensin system, including adrenocorticotrophic hormone, renin, angiotensin II (Ang II), and aldosterone, were detected in 28 patients." (PMID 33909683, 2021). "The renin–angiotensin–aldosterone system (RAAS) hormonal cascade is one of the most significant pathways to preserve hemodynamic stability, with ACE as the key enzyme in this mechanism to control hypertension." (PMID 33429899, 2021). "Neither hypertension nor the use of renin-angiotensin system blockers (RAABs) was significantly associated with severity." (PMID 34016150, 2021). "In animal model, lacking the VitD receptor (VDR) has elevated production of renin and angiotensin II, leading to hypertension." (PMID 33827712, 2021). "The renin–angiotensin system (RAS) is a key regulator of blood pressure and hypertension." (PMID 34769093, 2021). "Other reports showed that only PAC and not plasma renin activity (PRA) was elevated and associated with obesity and hypertension." (PMID 34675881, 2021). "Through interactionswith the renin–angiotensin–aldosteron system, VAL maybe used to treat both hypertension and the current pandemic coronavirusSARS-CoV-2 infection." (PMID 33792313, 2021). "We are the first to provide an elaborate TAC study of progressive heart failure that assesses both, acute and progressive effects of heart failure on renal function in relation to renin expression in the absence of systemic hypertension." (PMID 34211391, 2021). "S1P inhibition significantly attenuated Ang II–induced hypertension accompanied with suppressed urinary and renal medullary renin levels and expression of renal medullary but not renal cortical α-ENaC expression." (PMID 33280408, 2021). "The majority of patients with combined 17α-hydroxylase/17,20-lyase deficiency due to severely inactivating CYP17A1 mutations first present with a lack of pubertal development and low renin hypertension." (PMID 34524979, 2021). "These products may disrupt homeostasis of endothelial and smooth muscle cells through activation of renin–angiotensin–aldosterone system (RAAS), thereby accelerating the damage to the vascular wall and kidney that lead to hypertension." (PMID 34749652, 2021). "Hypertension in patients with preeclampsia is not mediated by the renin-angiotensin-aldosterone system." (PMID 35186968, 2021). "In order to compare the present case with other cases concerning the distribution of renin at the vascular pole of the glomerulus, a case of diabetes mellitus glomerulopathy at the same age without hypertension was used." (PMID 33546619, 2021). "The grade or occurrence of peripheral edema and hypertension in patients who consumed licorice did not correlate well with laboratory abnormalities, such as hypokalemia, low renin activity, aldosterone concentration, and GL metabolites." (PMID 34604277, 2021). "It is well known that in the hyperactive brain renin–angiotensin system (RAS), oxidative stress and neuroinflammation in brainstem cardiovascular centers and other brain regions increase sympathetic activity in hypertension." (PMID 35366276, 2021). "In a study including 101 patients with or without diabetes mellitus and hypertension, urinary renin did not correlate with plasma renin and especially dissociated in patients with diabetes mellitus or on RAS-inhibitors." (PMID 33382448, 2021).
Hypertension (continued). "While glycaemic control and diagnosis of hypertension did not improve over time, the use of statins among patients diagnosed with dyslipidaemia and renin–angiotensin system inhibitors (RASis) among patients diagnosed with hypertension increased." (PMID 33594476, 2021). "For example, HRP can alleviate organ damage and eyeball diseases caused by diabetes and hypertension, but it does not reduce the hypertension of renin and angiotensinogen (AGT) overexpressing rats." (PMID 34057312, 2021). "The SHR is considered to be a renin-independent model of hypertension in which plasma AngII levels are not elevated." (PMID 34711215, 2021). "We report a case of hypertension and hypokalemia with a negative plasma aldosterone/renin ratio, inconclusive confirmatory saline infusion test." (PMID 34926077, 2021). "Page kidney or Page phenomenon is the result of subcapsular or extracapsular blood or fluid accumulation causing compression of the kidney parenchyma, resulting in decreased renal perfusion, activation of the renin‐angiotensin‐aldosterone system (RAAS), and hypertension." (PMID 34216535, 2021). "Recently, it has been shown that renin-angiotensin system regulators have a pleiotropic role in the central nervous system (CNS), independent of their regulation of hypertension." (PMID 34697992, 2021). "In patients with essential hypertension, beta-blocker treatment led to a highly significant suppression of renin, whereas PAC was not significantly altered." (PMID 34054559, 2021). "Bartter syndrome is also characterized by hypokalemia, metabolic alkalosis, polyuria, increased renin activity and aldosterone levels, but without hypertension or edema." (PMID 32758178, 2020). "Accumulating evidence indicates that renin-angiotensin system (RAS) components and inflammatory mediators act on brain nuclei within a central neural network to increase SNS drive that in turn, generates hypertension." (PMID 32760236, 2020). "Since the renin-angiotensin-aldosterone system (RAAS) has an important role in development of human DN, several studies have used a transgenic rodents with overactivated RAAS to induce hypertension and accelerated DN." (PMID 32566684, 2020). "On this basis, various forms of monogenic hypokalemic hypertension commonly manifest as early-onset refractory hypertension, profound hypokalemia and metabolic alkalosis; except for pheochromocytoma (PCC), all forms of monogenic hypertension also have low levels of renin." (PMID 33569358, 2020). "Mounting evidence indicates that the renin-angiotensin (RAS) and immune systems interact with one another in the central nervous system (CNS) and that they are importantly involved in the pathogenesis of hypertension." (PMID 32760236, 2020). "These peptides may reduce hypertension by inhibiting ACE and/or renin activities, triggering nitric oxide production, or blocking angiotensin II receptors." (PMID 32726971, 2020). "Activation of the renin-angiotensin-aldosterone system (RAAS) in adipose tissue may represent an important link between obesity and hypertension." (PMID 32257423, 2020). "Orally active ACE inhibitors are effective antihypertensive agents, not only in high-renin hypertension but also in clinical and experimental models that do not involve the systemic RAS." (PMID 33126450, 2020). "Myeloid cells are known mediators of hypertension, but their role in initiating renin-induced hypertension has not been studied." (PMID 32968066, 2020). "It was suggested that activation of the renin-angiotensin-aldosterone system (RAAS) in adipose tissue may represent an important link between obesity and hypertension." (PMID 32257423, 2020). "For example, in the transgenic Ren2 rat preclinical model of hypertension, tissue RAS overexpression with increased renin and Ang II (10 weeks of age) demonstrated that only the islets were stained excessively with 3-nitrotyrosine as compared to the Sprague–Dawley control age-matched controls." (PMID 33202960, 2020).
Hypertension (continued). "The renin-ACE-Ang II-AT1 receptor pathway is responsible for the major pressor physiological actions of vasoconstriction, Na + retention, and aldosterone release, which become detrimental in cardiovascular diseases such as hypertension and heart failure." (PMID 32880756, 2020). "Our data indicate that in the CD, low NO levels stimulate CD-renin synthesis and secretion, thus leading to an inappropriate intratubular RAS activation, which may contribute to the development and progression of hypertension." (PMID 33281610, 2020). "The development of hypertension in T2DM involves multiple processes, including enhanced sympathetic output, inappropriate activation of renin-angiotensin- aldosterone system, endothelial dysfunction induced through insulin resistance, and abnormal sodium handling by the kidney." (PMID 31733658, 2019). "Economic studies have shown promising positive evidence of cost-saving and/or cost-effectiveness of implementing early treatment of renin-angiotensin system inhibitors (RAS) drugs to prevent the progression of nephropathy in patients comorbid with diabetes and hypertension." (PMID 30817790, 2019). "In addition to the peripheral RAS, a separate renin-angiotensin system within the CNS has been reported to contribute to the hypertension of animal models including SHR, phenol renal injury hypertension model, and cold-induced hypertension." (PMID 31681017, 2019). "Therefore, endogenous pressor substances, such as those that constitute the renin-angiotensin system (RAS), are the main targets for the development of a hypertension vaccine." (PMID 31485348, 2019). "Many classes of drugs are currently used to treat hypertension as a monotherapy or in combination, for example, diuretics, ß blockers, angiotensin-receptor blockers (ARB), renin inhibitors, angiotensin-converting enzyme inhibitors, and calcium-channel blockers." (PMID 31772615, 2019). "In spontaneously hypertensive rat (SHR), early therapy with aliskiren, a renin inhibitor, has been reported to reduce ADMA, restore l-arginine-to-ADMA ratio, and increase renal cortical nNOS protein level to prevent the development of hypertension." (PMID 30764498, 2019). "Previous studies characterizing the Cx40−/− mouse have reported a perturbed negative feedback of renin secretion, despite exhibiting severe hypertension." (PMID 30745457, 2019). "Firstly, due to its constitutive overexpression of human pro-renin, the Ren+/− mouse develops hypertension at an early age, unlike most humans with diabetic kidney disease, in whom hypertension usually develops later in life." (PMID 31467329, 2019). "The effects of the renal sympathetic nerves on renal tubular reabsorption of sodium, renin release, and glomerular filtration rate are now seen to provide hypertension-producing mechanisms but without affecting renal hemodynamics." (PMID 31920690, 2019). "In addition to high blood pressure, it is well recognized that the renin–angiotensin–aldosterone system (RAAS) and vascular inflammation induce renal oxidative stress under the pathophysiology of hypertension." (PMID 30542084, 2019). "Hypertensive patients in these two studies all shared certain similarities including near-universal low or undetectable plasma renin activity (PRA), presentation of high blood pressure around 35–40 weeks postmenstrual age (PMA), and an excellent response to treatment with spironolactone." (PMID 31028470, 2019). "This study investigated the long-term antihypertensive effects of esaxerenone, a novel nonsteroidal mineralocorticoid receptor blocker, alone or in combination with a calcium channel blocker (CCB) or a renin–angiotensin system (RAS) inhibitor, in Japanese patients with essential hypertension." (PMID 31554937, 2019). "IgG antibody titers were not correlated with TNF-α, NOX4, renin, and NO in hypertension subjects in any of the models (P>0.05)." (PMID 29752343, 2018).
Hypertension (continued). "Most of these predictors (except for serum concentrations of cystatin C, NGAL, and uromodulin) were independent of age, diabetes duration, the presence of hypertension, heart failure, and the treatment with renin-angiotensin-aldosterone system inhibitors." (PMID 30158836, 2018). "Therefore, renin and/or ACE I inhibition are considered the main targets for hypertension treatment and many research works have been published about natural and synthetic compounds inhibiting RAS." (PMID 30011911, 2018). "Shortly after Jerome Conn first described primary aldosteronism as a condition of aldosterone excess independent of renin, a phenotype of low renin activity in hypertension without overt hyperaldosteronism was described." (PMID 29439489, 2018). "Therefore, vitamin D analogs have been suggested to be used as renin inhibitors similar to ACE inhibitors and ARBs for patients with hyperreninemia, which can benefit patients with metabolic syndrome and/or hypertension." (PMID 29977597, 2018). "None of the studied markers differed significantly between men and women, between patients with and without hypertension, or between those treated and not treated with renin-angiotensin-aldosterone inhibitors." (PMID 30158836, 2018). "Due to the well-known involvement of the renin-angiotensin-aldosterone system (RAAS) system on arterial pressure regulation, the effects of epigenomic regulation of the RAAS system have been extensively tested in animal models of systemic hypertension." (PMID 29649151, 2018). "In models of hypertension, CGRP protects against the onset and progression of hypertensive states by potentially counteracting against the pro-hypertensive systems such as the renin-angiotensin-aldosterone system (RAAS) and the sympathetic system." (PMID 30283343, 2018). "Hyper-activity of the renin-angiotensin system (RAS), particularly angiotensin II (AngII), together with sympathetic nervous system over-activity contribute to the development and maintenance of hypertension." (PMID 29590257, 2018). "The genetic test is appropriate in the presence of early onset hypertension, hypokalemia, low renin and low aldosterone, with or without a positive family history." (PMID 29534496, 2018). "Thus, elevated renin levels in SHR, which is an established model of essential hypertension, have been reported in several studies." (PMID 29849899, 2018). "In both humans with hypertension and in SHR, both local and systemic renin-angiotensin-aldosterone systems are activated, which leads to increased expression of the Nox4 and/or Nox1 proteins and, consequently, to a pro-oxidant state resulting from chronically increased superoxide production 15-17." (PMID 28591344, 2017). "The renin-angiotensin-aldosterone system (RAAS) plays a fundamental role in the physiology of blood pressure control and the pathophysiology of hypertension (HTN) with effects on vascular tone, sodium retention, oxidative stress, fibrosis, sympathetic tone, and inflammation." (PMID 28413612, 2017). "Renin (EC 3.4.23.15) converts angiotensinogen to angiotensin I, and it will be converted to biologically active angiotensin II by angiotensin-I converting enzyme (ACE, peptidyldipeptide hydrolase, EC 3.4.15.1), which ultimately leads to hypertension." (PMID 28282929, 2017). "Angiotensin-I-converting enzyme (ACE-I) is a proteolytic enzyme that affects vasoconstriction in two major blood pressure regulatory systems, namely renin-angiotensin–aldosterone system (RAAS) and kinin–kallikrein system, leading on to the development of hypertension." (PMID 28445408, 2017). "We found that expression of a 15-kb human RENIN (hREN) transgene was aberrantly upregulated (>4.2-fold), while the endogenous mouse renin (mRen) gene was suppressed (>1.7-fold) in Tsukuba hypertensive mice (THM), a model for genetically induced hypertension." (PMID 27861631, 2016).
Hypertension (continued). "CD specific renin KO mice were not protected from DOCA-salt induced hypertension or renal injury suggesting that CD renin is not likely to be involved in DOCA-salt hypertension." (PMID 27467376, 2016). "None of the REN gene polymorphisms exhibited a confounding effect on the relationship between CKD progression and hypertension." (PMID 26753721, 2016). "The activation of renin-angiotensin system (RAS) is considered not only as a main hypertensive system, but also as a key factor triggering reactive oxygen species production, oxidative stress, endothelial dysfunction and hypertension development." (PMID 28105924, 2016). "Similarly, in the mRen2.Lewis rat model of tissue renin overexpression, a dual blockade of RAS with an ACEI and an ARB in young pre-hypertensive rats prevents the development of hypertension and the appearance of diastolic dysfunction." (PMID 27420103, 2016). "Female TASK1-/- mice lacking KCNK3 develop hypokalemia and low-renin hypertension that is normalized by mineralocorticoid receptor blockade but controlled by ACTH, a consequence of misallocation of aldosterone synthase in the zona fasciculate." (PMID 27736895, 2016). "The renin-angiotensin system (RAS) becomes activated in diabetes, hypertension and heart failure." (PMID 27536244, 2016). "In summary, the current study demonstrates that CD renin is not essential to the hypertension or renal injury associated with DOCA-salt treatment, which is one form of low Ang-II hypertension." (PMID 27467376, 2016). "We prevented hypertension development in adult offspring exposed to maternal HF diet by using three deprogramming approaches, namely, melatonin, soluble epoxide hydrolase (SEH) inhibitor, and renin inhibitor aliskiren." (PMID 27897982, 2016). "The absence of hypertension discounted consideration of a primary renin secreting tumor or of renin stimulation from a renovascular disease such as fibromuscular dysplasia." (PMID 27579038, 2016). "Fourth, we could not measure hepatokines such as fetuin-A, fibroblast growth factor 21, and selenoprotein P and levels of renin, angiotensin II and aldosterone which could explain the mechanism for an independent role of NAFLD in incident hypertension." (PMID 26618774, 2015). "The ADPN-induced decrease in BP is probably related to the renin-angiotensin system and the sympathetic nervous system; in addition, the impact of ADPN on vascular tension appears to be independent of other hypertension risk factors." (PMID 26389928, 2015). "The long term regulation mechanisms relate to humoral systems, such as renin-angiotensin system (RAS) whose unbalance contributes to the development/maintenance of high peripheral resistance and vascular hyper-reactivity observed in hypertension." (PMID 26388783, 2015). "Mice lacking vitamin D receptor had an increased renin expression and angiotensin II production and developed also hypertension and cardiac hypertrophy." (PMID 26000280, 2015). "The ADX improved her hypertension with normalization of the plasma aldosterone concentration, but without adequately increasing her plasma renin activity." (PMID 24343173, 2015). "Here, there are hypertension and hyper-secretion of renin, but not high concentration of aldosterone and hypokalemia." (PMID 28509110, 2015). "Hypertension is related to TGF-β1, because increased TGF-β1 expression is correlated with an elevation in arterial pressure (AP) and TGF-β expression is upregulated by the renin-angiotensin-aldosterone system." (PMID 26398936, 2015). "Taken together, these results indicate that the development of pulmonary fibrosis is mainly attributed to the high renin activity in the transgenic mice, but is independent of the high blood pressure." (PMID 26494430, 2015). "One important question is whether the pulmonary fibrosis seen in these transgenic mice is a consequence of renin increase, activation of Ang II-AT1 signaling pathway or high blood pressure." (PMID 26494430, 2015).